OR52K1 (olfactory receptor family 52 subfamily K member 1)
Description:
Odorant receptor.
Synonyms: OR11-8
Tractability: Antibody: UniProt places it where antibodies can reach, with medium confidence; UniProt predicts a signal peptide or a membrane-spanning region; its Gene Ontology location is reachable by antibodies, with medium confidence.
Gene: Protein-coding gene on chromosome 11 (4,482,646 to 4,493,497, forward strand). Ensembl gene ENSG00000196778.
Subcellular location: Cell membrane
Pathways (Reactome):
Sensory Perception: Expression and translocation of olfactory receptors
Gene Ontology:
Molecular function: olfactory receptor activity; G protein-coupled receptor activity
Biological process: detection of chemical stimulus involved in sensory perception of smell; G protein-coupled receptor signaling pathway; nervous system process
Cellular component: plasma membrane; membrane
Genetic constraint (gnomAD): Loss-of-function variants: 14 observed, 11.87 expected, observed/expected ratio (o/e) 1.18, 90% interval 0.77 to 1.77. The synonymous counts are far from expectation, so gnomAD's model fits this gene poorly and the ratio says little. Missense variants: 424 observed, 406.26 expected, observed/expected ratio (o/e) 1.04, 90% interval 0.96 to 1.13. Synonymous variants: 200 observed, 151.82 expected, observed/expected ratio (o/e) 1.32, 90% interval 1.17 to 1.48.
Homologues: Orthologues: macaque OR52K1 (95% identical), rat Or52k1 (89% identical), dog OR52K1B (87% identical), rabbit OR52K1 (87% identical). Paralogues in human: OR52K2 (91% identical), OR52E8 (53% identical), OR52L1 (52% identical), OR51G2 (52% identical), OR52N4 (51% identical), OR52J3 (51% identical), OR52D1 (50% identical), OR52E6 (50% identical), OR52R1 (50% identical), OR51C1 (50% identical), OR52B2 (50% identical), OR52B6 (50% identical), and 39 more.
Diseases named in the same sentence as OR52K1 in open-access papers:
OR52K1 is named in the same sentence as 2 diseases in open-access papers, as found by Europe PMC text mining. Sharing a sentence is not in itself a finding about the gene and the disease. The quoted sentences say what the papers report.
Obesity (1 paper, 2023). Accumulation of substantial excess body fat. "OR4D1, and OR52K1 gene scores were positively correlated with obesity, and OR2L8 and CALML3 gene scores were negatively correlated with obesity." (PMID 37664850, 2023).
OR52K1 also shares sentences with these, for which no sentence is quoted: cardiac disease (1 paper).